EGF (epidermal growth factor)
Diseases named in the same sentence as EGF in open-access papers (continued):
Sharing a sentence is not in itself a finding about the gene and the disease.
breast carcinoma (continued). "Binding of epidermal growth factor (EGF) to epidermal growth factor receptor (EGFR) leaded to the phosphorylation of CREB1 which resulted in a series of genes expression correlated with the progression of breast cancer." (PMID 31754343, 2019). "It is well known that ERα and EGF play an important role in breast cancer." (PMID 31430961, 2019). "Previously, we found that the collagen invasion and migration of pre-malignant breast cancer cells in response to TGFβ and epidermal growth factor (EGF) critically depend on multiple Jun and Fos components of the activator protein (AP)-1 transcription factor complex." (PMID 31766464, 2019). "Herein, we illustrated a novel mechanism of PN-1 promoting breast cancer metastasis by binding and blocking HtrA1, which could cleave extracellular EGF and suppress cancer cell EMT." (PMID 31501409, 2019). "MDA-MB-468 breast cancer cells induced to undergo EMT by treatment with 20 ng/mL of epidermal growth factor (EGF) were initially passed through several blockages and then through a constricted microchannel, mimicking the flow of invasive metastatic cells through constricted blood microcapillaries." (PMID 31404980, 2019). "However, despite these findings, the effects on transcription following long term EGF stimulation of EGFR (> 20 min) and its underlying chromatin basis remains unexplored in HER2+ breast cancer cells." (PMID 30736768, 2019). "This fundamental change in response to EGF through breast cancer progression led us to address the hypothesis that pharmacological biasing of downstream signaling could reveal apoptotic EGFR signaling, even in early-stage breast cancer." (PMID 30250119, 2018). "In a sophisticated ex vivo microphysiological model of breast cancer metastasis to the liver, breast cancer outgrowth in response to an inflammatory lipopolysaccharide/EGF stimulus could be suppressed with atorvastatin treatment." (PMID 30458856, 2018). "Similarly, increased expression of NgBR in tamoxifen-resistant breast cancer cells also enhances EGF-stimulated Ras activation and phosphorylation of AKT and ERK." (PMID 30208932, 2018). "Yu et al4 showed that silencing ATF6α inhibits EGF‐induced breast cancer cell proliferation." (PMID 30414263, 2018). "To determine whether PTPN5 controls EGF-induced MAPK signaling in human breast cancer cells, we assessed the phosphorylation status of MAPK in various breast cancer cells by forced expression of PTPN5." (PMID 29590203, 2018). "In addition, PIP5Kα gene disruption inhibited epidermal growth factor (EGF)‐induced Akt activation and caused significant proliferation defect in breast cancer cells." (PMID 29851245, 2018). "Experimental evidence in breast cancer and other cell lines suggests that steroids and growth factor signaling pathways such as EGF and IGF-1 have synergistic effects in inducing cell proliferation and that cross-talk between these pathways is important in estrogen action." (PMID 30400783, 2018). "In 1994, Wollman et al2 found that treatment of breast cancer MCF‐7 cells with epidermal growth factor (EGF) before irradiation could stimulate cell proliferation and increase their radiation resistance." (PMID 29856131, 2018). "Breast cancer is closely related to hormone signaling and EGF signaling and could be divided into several subtypes based on the expression of ER, PR, and HER2." (PMID 30544991, 2018). "First, in breast cancer cells, growth factors other than EGF and HGF may trigger the activation of the MAPK signaling pathway, which includes ERK1/2." (PMID 30227653, 2018). "For example, altering actin nucleation rates can modulate the stress fluctuation magnitudes in the cytoskeleton, a phenotype observed in intracellular microrheology experiments that modulate epidermal growth factor (EGF) signaling (known to influence actin nucleation) in breast cancer cells." (PMID 30105089, 2018).
breast carcinoma (continued). "EGF and the EGF receptor EGFR (HER1) have been extensively studied in cancer, with EGFR amplification implicated in the pathogenesis of lung cancer, glioblastoma, and breast cancer, among others." (PMID 30158935, 2018). "Moreover, the sensitivity of breast cancer cells to atorvastatin-mediated growth suppression correlated with a decrease in EGF-mediated phosphorylation of Akt." (PMID 29763460, 2018). "In cell culture, breast cancer cells with secondary resistance to trastuzumab displayed an up-regulation of mRNA expression for EGF, TGFα, HB-EGF and heregulin, while the expression of AREG mRNA was downregulated and the expression of epiregulin and betacellulin mRNA was unchanged." (PMID 27933395, 2017). "Moreover, S100A4 was able to combine with the Rhotekin–RhoA complex to promote membrane ruffling and invasion of epidermal growth factor (EGF)-expressed breast cancer cells." (PMID 29069865, 2017). "EGR2 is expressed in breast cancer cell lines, particularly the more aggressive triple negative subtypes and may be regulated in part by Epidermal Growth Factor (EGF) family members." (PMID 28687085, 2017). "In addition, BMP-6 in breast cancer cells can be upregulated by EGF and other EGFR ligands such as transforming growth factor-α, amphiregulin and betacellulin." (PMID 28733469, 2017). "Our results suggest that FOXC1 may serve as a readout of EGF-NF-κB signaling activity in breast cancer." (PMID 28629477, 2017). "In a murine model of breast cancer, TAMs are also demonstrated to promote CSC phenotypes in breast cancer cells through the EGF-mediated STAT3/SOX-2 cascade, and this cross talk could be abrogated by small molecule inhibitors against EGFR or STAT3." (PMID 28337221, 2017). "This miRNA is an epidermal growth factor induced miRNA, and its association with breast cancer has not been recorded by any existing databases." (PMID 28340554, 2017). "EGF has a higher expression and is correlated with the progression of cancer such as breast cancer." (PMID 28384236, 2017). "Moreover, EGF-induced FOXC1 expression occurs not only in breast cancer cells but also in prostate cancer cells." (PMID 28629477, 2017). "In breast cancer cells, the paracrine role of epidermal growth factor (EGF) and its receptor EGFR (ErbB-1) contribute to invasion, intravasation, and metastasis through activation of extracellular signal-regulated kinase 1/2 (ERK1/2), STAT3, or PI3K/Akt signaling, promoting the EMT." (PMID 29189742, 2017). "Thus, both WBP2 and WBP2NL genes are highly related to the angiogenesis of breast carcinoma through the modulation of EGF, ER, and other downstream signaling proteins." (PMID 28724435, 2017). "Of these, HBEGF is abundantly expressed in human adipose tissue, TGFα has been implicated in the development of obesity-related postmenopausal breast cancer using rodent models, and EGF has received much attention as a therapeutic target in anticancer therapies." (PMID 27525640, 2017). "Interestingly, while mammosphere formation was insensitive to added hormones, EGF was required for spheroid formation in breast cancer cells expressing K388R (phospho-mimic) PRs." (PMID 28412963, 2017). "However, clinical trials with inhibition of EGF/IGF signaling or PI3K activity are either suboptimal or even disappointing with respect to inhibition of breast cancer progression." (PMID 28451590, 2017). "DDX21 promotes c-Jun activity by EGF signaling in the tumorigenesis of breast cancer." (PMID 27835882, 2016). "Because growth factors play essential roles in both mammary gland development and in breast cancer progression, and long noncoding RNAs (lncRNAs) are emerging as cardinal regulators of gene expression, we profiled epidermal growth factor (EGF) inducible expression of lncRNAs in normal mammary cells." (PMID 27485121, 2016). "Recently, miR-675 is demonstrated to activate EGF signaling pathway in breast cancer." (PMID 27120794, 2016).
breast carcinoma (continued). "SOCE has been reported to be involved in TGF-β or EGF-induced EMT in breast cancer cells." (PMID 27677589, 2016). "Hence, expression of the EGF‐inducible lncRNAs we uncovered was examined in large cohorts of breast cancer patients, with the vision of identifying potential drivers and biomarkers of the basal‐like and the HER2‐enriched subtypes." (PMID 27485121, 2016). "The affinity of the receptors for EGF is much higher in ER-positive breast cancer cell lines." (PMID 27564112, 2016). "The mechanism of EGF-induced EMT via activation of the Smad2/3 in breast cancer cells, MCF-7 and MDA-MB-231, remains unclear." (PMID 27829223, 2016). "Taken together, our studies have demonstrated essential role of ERα and STAT5b in EGF/EGFR induced activation of PRLR gene transcription/expression in breast cancer cells via STAT5b interaction with ERα and complex formation with Sp1/C/EBPβ at the PRLR promoter in the absence of estrogen." (PMID 27564112, 2016). "Thus, extension of lamellipodia toward EGF during chemosensing by breast carcinoma cells requires the Lpd-dependent recruitment of Ena/VASP proteins, despite the dispensability of Ena/VASP for Lpd-driven random 2D cell migration." (PMID 26996666, 2016). "Considering the emerging roles for long noncoding RNAs (lncRNAs) in metastasis of breast cancer, we raised the possibility that some EGF‐inducible lncRNAs might play a role in basal‐like breast cancer." (PMID 27485121, 2016). "Moreover, we determine a novel link between RAB35 and MICAL1 in regulating EGF-induced breast cancer cell invasion." (PMID 27430308, 2016). "This led to the identification of a subset of eleven EGF‐regulated lncRNAs, the expression patterns of which could be used to predict survival time of breast cancer patients." (PMID 27485121, 2016). "In fact, using a metastatic breast cancer model it was possible to comprehend that the paracrine loop signaling between TAMs, which supply EGF, and breast cancer cells, which on the other hand supply CSF1, is sufficient for the promotion of invasion and migration." (PMID 28053982, 2016). "Recent studies including the results from our laboratory showed that EGF treatment also could induce Arf6 activation and increased breast cancer cell migratory potential." (PMID 25678857, 2015). "In breast cancer, EGF stimulation has been shown to reduce C/EBPβ activity by increasing LIP." (PMID 25767874, 2015). "Recent studies including the results from our laboratory showed that Arf6 activation could be induced by EGF and act as a mediator of cell migration and invasion in various types of cancer including breast cancer cells." (PMID 25678857, 2015). "Thus, E2 and EGF cues are obligatory in the proliferation of ductal epithelial breast cancer cells and they have synergistic effects." (PMID 26258011, 2015). "A concentration-dependent effect of EGF on breast cancer cell proliferation has also been proposed." (PMID 26258011, 2015). "Rab5C plays a role in enhancing EGF-induced invasion by breast cancer cells." (PMID 25472813, 2015). "Arf6 may function on its GTP-bounded status to promote EGF-stimulated E-cadherin internalization in breast cancer cells." (PMID 25678857, 2015). "Such inhibition of MMP-9 by EGF was also observed in human breast cancer cell lines." (PMID 25897433, 2015). "Therefore, our results suggest that Arf6 activation serves as a mediator of EGF-stimulated E-cadherin internalization in breast cancer cell." (PMID 25678857, 2015). "Finally, miR-663 decreases in abundance at 3h and 12 h post EGF treatment and has previously been shown to mediate chemo-resistance of breast cancer cells by suppressing the apoptotic pathway." (PMID 25781916, 2015). "Our results indicate that Arf6 plays an important role in the regulation of E-cadherin internalization in response to EGF, and suggest that Arf6 may exert its function by physically interacting with E-cadherin in breast cancer." (PMID 25678857, 2015).
breast carcinoma (continued). "In breast cancer cells, epidermal growth factor (EGF) and amphiregulin induced the expression of CD147 via an EGF receptor (EGFR) pathway and transforming growth factor β (TGF-β) increased CD147 expression in a phosphatidylinositol 3-kinase (PI3K)-Akt-dependent manner in hepatocytes." (PMID 26604323, 2015). "Thus, EGF at concentrations that stimulate most other cell lines reduced the growth of MDA-468 breast cancer cells." (PMID 26258011, 2015). "The ER suppression in breast cancer cells prevents both EGF (and E2) stimulation of DNA synthesis." (PMID 26258011, 2015). "Nevertheless, the mechanism through which Anxa2 promotes EGF-induced EMT in breast cancer cells remains unknown." (PMID 26307676, 2015). "There is no specific drug for TNBC, although hormone therapy is established for the treatment of ER+ breast cancer, and lapatinib, a small molecule inhibitor for human epidermal growth factor receptor 2, is employed for HER2 breast cancer, which also inhibits epidermal growth factor (EGF) receptor." (PMID 26141684, 2015). "Mena11a expression in breast cancer cells causes formation of a poorly metastatic tumor which does not respond to EGF signaling in vivo." (PMID 26112005, 2015). "Indeed, EBP50 can suppress EGF-induced proliferation of breast cancer cells by inhibiting EGFR phosphorylation and blocking EGFR downstream signaling." (PMID 26258011, 2015). "SPA treatment also caused a significant reduction in EGF-induced cell cycle progression, which was accompanied by the reduced expression of cyclin D1 and CDK4 and a corresponding increase in p21 and p27 levels in MDA-MB-231 breast cancer cells." (PMID 24736807, 2014). "Importantly, OSM is co-expressed with EGF by TAMs, and the levels of secreted OSM are strongly correlated with levels of secreted EGF in breast cancer patients." (PMID 24675570, 2014). "In this report, we analyzed the whole genome expression dynamics (22035 probes and 18 time points) that accompanied MCF-7 (human breast cancer) cell proliferation and differentiation through the activation of ErbB receptor by epidermal growth factor (EGF) and heregulin (HRG), respectively." (PMID 24831017, 2014). "As previously reported, MIF expression may be induced by epidermal growth factor (EGF) in breast cancer cells and also appears to be involved in the proliferative pathway activated by EGF." (PMID 25289107, 2014). "EGF induced the associations of Gi3α with p-EGFR, Gab1 and Shp2 in breast cancer cells." (PMID 24521094, 2014). "In breast cancer, for example, some tumour cells migrate towards epidermal growth factor (EGF)." (PMID 25313567, 2014). "Moreover, our results show for the first time that CXCL12 expression is negatively regulated by EGF signaling in breast cancer cells." (PMID 24906407, 2014). "Sensitivity to ErbB1-4 ligands is a dominant feature of the breast cancer cell lines we examined: all 39 lines exhibited a statistically significant response to at least one ErbB ligand (EGF, EPR, BTC, or HRG) and 31 of the 39 lines responded to all four ligands." (PMID 24655548, 2014). "Interestingly, PKCι is essential for K-Ras-driven invasion in colon cancer by regulating Rac1, while aPKCs mediates EGF-induced cell migration of MDA-MB-231 breast cancer cells." (PMID 24887021, 2014). "In this study, the genome-wide dynamical profile of gene expression was analyzed for MCF-7 breast cancer cells induced by two distinct ErbB receptor ligands: epidermal growth factor (EGF) and heregulin (HRG), which drive cell proliferation and differentiation, respectively." (PMID 24831017, 2014). "In another study, it was shown that salivary protein factors such as vascular endothelial growth factor, epidermal growth factor, and carcinoembryonic Ag were elevated in breast cancer patients compared to healthy subjects, hence making it a possible biomarker for breast cancer detection." (PMID 25276835, 2014).
breast carcinoma (continued). "Taken together, these observations suggest that a relatively high subpopulation of luminal breast cancer patients may experience coexposure to TNFα + Estrogen + EGF and may thus acquire increased metastatic rate." (PMID 24369447, 2013). "For instance, it has been shown that PI3Kδ is the most important class IA PI3K in the regulation of EGF-driven motility of breast cancer cells, whereas PI3Kβ is required for directed migration but PI3Kα does not appear to play a role in breast cancer cell migration." (PMID 23320409, 2013). "Breast cancer patients undergoing FEC60 showed alterations in the intestinal permeability, which was associated with modifications in the levels of GLP-2, ghrelin and EGF." (PMID 23379680, 2013). "Indeed, EGF has previously been reported to increase the motility of several breast cancer cell types that express or over-express ErbB receptors." (PMID 23527039, 2013). "NSFL1C is a substrate of EGF signaling during breast cancer development." (PMID 23555679, 2013). "Finally, Smad7 was suggested to negatively regulate the EGF signaling pathway in breast cancer cells as ectopic Smad7 expression in SKBR3 cells completely abrogated EGF-induced MMP-9 expression." (PMID 24317436, 2013). "On the other hand, EGF can stimulate the activity of SphK1 in breast cancer cells." (PMID 24970174, 2013). "Taken together, our findings show that breast cancer cell lines of increasing malignancy exhibit progressively more heterogeneous spatiotemporal speed and directionality profiles that can be differentially perturbed by EGF or LPA." (PMID 23527039, 2013). "Epidermal growth factor (EGF) was used to induce EMT in MDA-MB-468 breast cancer cells." (PMID 23890218, 2013). "In addition, CD151-silenced MCF-10A breast cancer cells expressing ErbB2 also showed reduced β4 integrin phosphorylation at S1424 in response to EGF stimulation." (PMID 23613949, 2013). "This is intriguing since Mena but not other Ena/VASP proteins have been implicated in EGF-dependent breast cancer invasion and metastasis." (PMID 24076656, 2013). "We speculated that EBP50 masked the EGFR phosphorylation site via steric hindrance, resulting in the retardation of EGFR downstream signaling activation, thus suppressed EGF-induced proliferation of breast cancer cells." (PMID 22476347, 2012). "Mena11a expression in breast cancer cells causes formation of poorly metastatic tumors with a highly epithelial architecture that are not capable of responding to EGF chemotactic cues in vivo." (PMID 22971274, 2012). "EGF has been identified as a novel EMT inducer in human breast cancer." (PMID 23185433, 2012). "Then, we also explored whether EBP50 expression could inhibit EGF-induced AKT phosphorylation in breast cancer cells." (PMID 22476347, 2012). "The results show complex influence of EGF on the development of breast cancer." (PMID 22433566, 2012). "Therefore, the goal of this study was to further elucidate the role of EBP50 on EGF-induced breast cancer cell proliferation and EGFR signaling in breast cancer cells." (PMID 22476347, 2012). "Targeting EGF receptor tyrosine kinase activity by erlotinib resulted in significant inhibition of both pII cell proliferation and directional invasion towards EGF suggesting that this drug has potential therapeutic usefulness for preventing spread of particularly endocrine resistant breast cancer." (PMID 22860018, 2012). "Several reports have confirmed the role of EGF in breast cancer cell migration and invasion." (PMID 22860018, 2012). "To test whether the ERβ1-EGFR interaction is a critical regulator of EMT in basal-like breast cancer cells, we treated the ERβ1-expressing cells with EGF or the EMT inducer TGF-β1 for 24 h." (PMID 23158001, 2012). "In summary, this study demonstrated that EBP50 expression could inhibit EGF-induced breast cancer cell proliferation by blocking EGFR phosphorylation and its downstream signaling." (PMID 22476347, 2012).